ENSG00000267157 (novel protein)
Gene: Protein-coding gene on chromosome 19 (5,784,005 to 5,785,619, reverse strand). Ensembl gene ENSG00000267157.
Genetic constraint (gnomAD): Loss-of-function variants: 5 observed, 5.81 expected, observed/expected ratio (o/e) 0.86, 90% interval 0.45 to 1.69. That is too few expected variants to judge how well the gene tolerates losing a copy. Missense variants: 98 observed, 94.12 expected, observed/expected ratio (o/e) 1.04, 90% interval 0.88 to 1.23. Synonymous variants: 50 observed, 39.38 expected, observed/expected ratio (o/e) 1.27, 90% interval 1.01 to 1.61.